JAK2 (Janus kinase 2)
Diseases named in the same sentence as JAK2 in open-access papers (continued):
Sharing a sentence is not in itself a finding about the gene and the disease.
cancer (continued). "Taken together, these findings demonstrated that the novel dual inhibitors AJI-214 and AJI-100 potently inhibit the activities of Aurora A, Aurora B and JAK2 in intact human cancer cells." (PMID 24930769, 2014). "AG490 is a well-known JAK2 inhibitor which is able to effectively block STAT3 activation in different cancer cell lines." (PMID 24520293, 2014). "Combination of various PIM inhibitors with a JAK2 inhibitor results in significant synergistic growth inhibition of multiple MPN cancer cell lines and induction of apoptosis." (PMID 24830942, 2014). "Taken together, our data provide substantial evidence that dietary astaxanthin prevents the development and progression of HBP carcinomas through the inhibition of JAK-2/STAT-3 signaling and its downstream events." (PMID 25296162, 2014). "Our data support further investigation of SOCS2/3 as signalling effectors, prognostic indicators and potential therapeutic targets in cancers with JAK2 rearrangements." (PMID 23372669, 2013). "Amongst all the STATs signals, persistently activated STAT3 via IL-6 induced JAK2 activation promotes cancer cell proliferation, survival and invasion by promoting pro-oncogenic inflammatory pathways." (PMID 23690956, 2013). "Of the many mutations that characterize myeloid malignancies, some (TET2, ASXL1) can initiate a preleukemic clone, whereas others (MPL, JAK2) are phenotypic lesions that trigger the overt malignant disease." (PMID 23397042, 2013). "Accumulating evidence has reported the pro-inflammatory JAK2/STAT3 pathway plays an critical role in cancer metastasis, apoptosis and angiogenesis." (PMID 23690956, 2013). "We further assessed the potential effects of Icaritin on the status of JAK2, which is also frequently activated in cancer cells." (PMID 24324713, 2013). "Recent studies have pointed out that PPI activity is required for CypA-induced cell proliferation, and that several growth-related signaling molecules, including ERK1/2, Jak2, p38, and Stat5, are stimulated by CypA in cancer cells." (PMID 23031673, 2012). "A clinically relevant example of how the decreased LD lengths can affect impact SNP-tagging is observed in the BRCA1 and JAK2 cancer genes." (PMID 22811759, 2012). "The study of STAT3 in cancer has revealed that JAK2/STAT3 was activated in starved Hela cells, with the activated STAT3 directly bound to IL-6 promoter to increase IL-6 mRNA and protein secretion." (PMID 22937006, 2012). "JAK2 inhibitors warrant further investigation for use alone or in combination with standard chemotherapy in treating human cancers with elevated JAK2 activity." (PMID 22384256, 2012). "Recently, inhibition of Janus kinase 2 (JAK2)/signal transducer and activator of transcription 3 (STAT3) signaling was shown to underlie the effects of Cuc family on inducing cell death in cancer." (PMID 21304528, 2011). "Instead, the IL-6 downstream signal pathways, including Jak2/Stat3, co-cooperated to control the IL-6 autocrine production in the cancer cells we tested." (PMID 21122157, 2010). "FLLL32 was more potent than curcumin and other reported JAK2/STAT3 inhibitors in the inhibition of cancer cell viability in our comparisons." (PMID 20712901, 2010). "This study was designed to determine the role of Jak2/Stat3 pathway in the regulation of IL-6 autocrine production in cancer cells." (PMID 21122157, 2010). "Leptin also stimulates growth and inhibits apoptosis of cancer cells, and may contribute to the increase in the incidence of different types of cancers that are observed in obese individuals, through the activation of JAK2-linked PI3K/Akt and MEK/ERK1/2 pathways." (PMID 21070531, 2010). "The signaling pathways Jak2/STAT3 as well as Src kinase signaling have been discussed to contribute to apoptosis sensitivity of carcinoma cells including HCC." (PMID 17014711, 2006).
cancer (continued). "Additionally, the JAK2/STAT3 pathway can interact with other pathways, such as the NF-κB and FOXO pathways, which are closely associated with cancer development." (PMID 40978029, 2025). "Furthermore, the JAK/STAT pathway is recognized as one of the twelve major cancer pathways, highlighting the importance of proper JAK2 regulation in maintaining normal cell function." (PMID 40332385, 2025). "Therefore, further research is needed on combination therapies involving JAK2 inhibitors and other anti-cancer agents for TNBC treatment." (PMID 40199813, 2025). "Activation of the p38 MAPK and JAK2/STAT3 signaling pathways have both been reported to increase the expression level of COX-2 in cancers, suggesting that UPF1 might regulate COX-2 expression by activating the p38 MAPK and JAK2/STAT3 pathways." (PMID 41293174, 2025). "However, aberrant activation of the JAK2/STAT3 pathway is frequently detected in various tumors and has been implicated in the genesis, angiogenesis, and metastasis of many cancers." (PMID 40978029, 2025). "Melittin downregulates cancer-progressive genes by inhibiting the JAK2/STAT3 pathway." (PMID 40243485, 2025). "Additionally, a difficult and well-known problem with targeting JAK2 is that the cancer cells treated with this type of inhibitors frequently develop resistance to them." (PMID 41031165, 2025). "The JAK2/STAT3 pathway plays a key role in the aggressiveness of several malignant tumors." (PMID 40944417, 2025). "Notably, AZ960—a novel Jak2 inhibitor—has been reported to effectively induce apoptosis in cancer cells." (PMID 40257955, 2025). "Additionally, CAF-derived IL-6 activates the JAK2/STAT3 pathway in cancer cells, inducing EMT and enhancing metastatic potential, thereby reinforcing a positive feedback loop that sustains IL-6 expression." (PMID 40718440, 2025). "Research has shown that phosphorylated DDR2 in cancer cells can activate the JAK2 (Janus kinase 2)/ERK pathway and may initiate the Ras and PI3K pathways." (PMID 40083325, 2025). "Therefore, a positive correlation has been demonstrated between enhanced expression and/or activity of JAK2 and tumorigenesis in many cancers." (PMID 38706884, 2024). "Similarly, CS-IVa-Be targets cancer cells through the inhibition of IL-6R, impacting the JAK2/STAT3 phosphorylation signaling pathway." (PMID 38699644, 2024). "Herein, it was hypothesized that JAK2 might be a potential target of flavonoids, cinnamic acids, and anthraquinones, leading to antiproliferative effects in cancer cells." (PMID 38706884, 2024). "At the same time, IL-17A secreted by cancer-associated neutrophils and cancer-associated fibroblasts (CAF) induces the expression of human antigen R (HuR) by activating the JAK2/STAT3 signaling pathway, which recognizes the mRNA encoding Snail and induces its translation." (PMID 39906741, 2024). "RIP–qRT-PCR confirmed the binding of ALKBH5 to JAK2 mRNA in cancer cells." (PMID 38872221, 2024). "Cancer cell-specific-targeting of JAK2/STAT3 or combinations with immunotherapy may be required for further evaluation of JAK2/STAT3 signaling as a cancer therapeutic target." (PMID 38297352, 2024). "The oncogenic role of JAK2 in other malignancies, including colorectal, non-small cell lung, ovarian, gastric, pancreatic, prostate, and renal cancers, has also been demonstrated." (PMID 38706884, 2024). "Fedratinib is a JAK2 inhibitor that sensitises P-gp-overexpressing drug-resistant cancer cells." (PMID 39065625, 2024). "Several reports have claimed that JAK2 inhibition might be a promising approach to diminishing cell proliferation and triggering apoptosis in cancer cells." (PMID 38706884, 2024). "We discovered that JAK2-MUT cancers had remarkably higher CYT scores (P < 0.001)." (PMID 38200372, 2024). "Thus, agents that suppress the activation of Jak2 or Stat3 have potential in the prevention and treatment of cancer." (PMID 37089712, 2023).
cancer (continued). "Signal molecular pathway of JAK2 played an important role in cancer metastasis of cancer." (PMID 37062850, 2023). "Among these bioactive compounds, hederagenin, isolated for the first time from the fruits of S. pobeguinii, selectively kills cancer cells with additional anti-inflammatory potential, and it interacts with JAK2 and COX-2 suggesting these proteins as its potential molecular targets." (PMID 37416061, 2023). "Our previous pan-cancer analysis predicted that RUNX1 mutations and JAK2 may have a synthetic lethal interaction." (PMID 37581927, 2023). "EGFR/JAK2/STAT5b is also included in PD-L1-dependent cancer cell proliferation, and targeting this signaling pathway in NSCLC could be interesting due to EGFR overexpression, which is highly associated with many NSCLC cells, including A549 and H460." (PMID 37998363, 2023). "The Jak2/Stat3 pathway is reported to be a key mediator for CSC functions in many kinds of cancers." (PMID 37089712, 2023). "In addition, it can activate Src, focal adhesion kinase FAK, STAT3, JAK2/STAT3/Snail (in cancer cells), signaling kinases correlated with cancer progression." (PMID 36835413, 2023). "Furthermore, it was observed that DLGAP5 also regulated the activity of the JAK2/STAT3 signaling pathway involved in cancer progression and development." (PMID 37958803, 2023). "Despite the finding that the suppression of WNT/β‐catenin signaling on account of ectopic PRDM5 expression was determined in limited cancer cell lines, we first explored and identified the inhibition of JAK2/STAT3 pathway in LUAD cell lines with PRDM5 overexpression." (PMID 36127737, 2023). "Furthermore, concomitant JAK2 and MEK1/2 inhibition reprograms the cancer-associated fibroblast (CAF) and immune microenvironment to overcome resistance to anti-PD-1 therapy in PDAC." (PMID 37210549, 2023). "Furthermore, to check the activity of azilsartan in both cancer cell lines at the molecular level, NF-kB/IL-6/JAK2/STAT3 signaling pathway was investigated." (PMID 36431925, 2022). "Activation of the Jak2/Stat3 signaling promotes cell proliferation and cell stemness in cancer." (PMID 35600882, 2022). "We also found similar degrees of early apoptosis between KBV20C cells treated with VIC–fedratinib, VIC–CEP-33779, and VIC–NVP-BSK805, indicating that co-treatment with JAK2 inhibitors can increase cytotoxicity in P-gp overexpressing resistant cancer cells by inducing early apoptosis." (PMID 35562984, 2022). "Two JAK1/JAK2 inhibitors have been considered for cancer therapy." (PMID 36358681, 2022). "Our findings on JAK2 inhibitors could be useful in the development of effective regimens for cancer patients with drug-resistance." (PMID 35562984, 2022). "Many studies demonstrated the role of JAK2 in various cancers." (PMID 35207737, 2022). "Hence, we investigated the expression of markers associated with the EMT process together with the expression status of p-JAK2 and cancer stem cell markers' (CSCs) markers." (PMID 35111269, 2022). "Interestingly, andrographolide is known to inhibit the actions of STAT3, JAK1, and JAK2 phosphorylation in human cancer cells." (PMID 35682652, 2022). "Indeed, activation of the JAK2/STAT3 signaling pathway has been reported in various types of cancers." (PMID 35589677, 2022). "Besides, ZQL-4c significantly inhibited the expression of phospho-STAT3 and phospho-JAK2 in three types of cancer cells." (PMID 35528507, 2022). "NCTD affects iron metabolism by modifying the expression of IL-6/JAK2/STAT3/hepcidin and IRP1 and suggest that the ability of NCTD to reduce tissue iron contents may be a novel mechanism associated with the anti-cancer effects of NCTD." (PMID 35735222, 2022). "Importantly, BCAT1, EGFR and JAK2 are required for cell proliferation signaling in cancer cells or preadipocytes." (PMID 35269469, 2022). "IL-6/JAK2/STAT3 signaling pathway deserves attention in the treatment of human cancer." (PMID 36591515, 2022).
cancer (continued). "Interestingly, the mRNA levels of its downstream pathway mediators, such as MAPK1, JAK2 and KRAS, were found to be negatively associated with their methylation levels in most cancer types." (PMID 35978072, 2022). "IL-12, vitamin D3, vitamin A, curcumin, and cucurbitacin B [a selective inhibitor of Janus kinase 2 (JAK2)/STAT3] are molecules that may induce MDSCs to differentiate into mature myeloid cells in several types of cancer." (PMID 36081407, 2022). "It is possible that other IL-6-like signals that activate the JAK2/STAT3 pathway are mediating some of the suppression in other cancer cells as treatment of cGAMP-unresponsive cancer cells with the JAK2/STAT3 inhibitor WP1066 upregulated type I IFN expression in the tested cancer cells." (PMID 33790360, 2021). "In addition, inhibition of JAK2/STAT3 signaling by introducing AG490 attenuated the cancer-promoting activity of THAP9-AS1." (PMID 34691358, 2021). "Moreover, IL-6 secreted by activated fibroblasts in cancer stroma induces EMT of gastric cancer cells via JAK2/STAT3." (PMID 34207510, 2021). "Here, by using T cell bispecific antibodies and chimeric antigen receptors (CAR) T cells targeting HER2, the authors show that cancer cell intrinsic disruption of interferon-gamma signalling, including downregulation of JAK2, confers resistance to T-cell mediated cytotoxicity." (PMID 33623012, 2021). "JAK2 is known to stimulate STAT3 phosphorylation on tyrosine Tyr705 in many cancer cells." (PMID 33995073, 2021). "According to recent studies, JAK2/STAT3 signaling pathway played critical roles in metastasis and progression of cancers, which implied that JAK2 might be a crucial therapeutic target for treatment of cancer." (PMID 33917914, 2021). "Furthermore, inhibition of JAK2/STAT3 signaling pathway using WP1066 effectively suppressed cancer cell proliferation, resistance to cisplatin, and DDR." (PMID 34496932, 2021). "Janus kinase 2 (JAK2)/signal transducer and activator of transcription 3 (STAT3) signaling pathway is believed as a crucial link implicated in invasion, survival, growth and angiogenesis of cancer cells." (PMID 33976735, 2021). "Thus, our current study supported that JAK2 has a potential to be an important target for various cancer treatment." (PMID 33917914, 2021). "Elevated GPR87 expression promotes cancer stem cell expansion by regulating the JAK2/STAT3 pathway." (PMID 34290570, 2021). "Furthermore, let-7 participates in the JAK2/STAT signaling pathway in cancer cells by targeting SOCS4 and activates the JAK1/STAT3 signaling pathway." (PMID 34568312, 2021). "Furthermore, recent studies have reported that the synthetic JAK2 inhibitor was considered as the therapeutic agent for other cancer types." (PMID 33917914, 2021). "Upregulation of LRG1 in cancer cells relied on JAK2/STAT3 signaling, we hypothesized that LRG1 could be a potential novel target regulated by STAT3." (PMID 34930899, 2021). "Collectively, these results suggest that 5-epi-sinuleptolide could inhibit the activities of key regulators for cancer progression including JAK2/STAT3, AKT, and ERK1/2, and suppress the invasiveness of malignant pancreatic cells." (PMID 34834023, 2021). "Since our GSEA analysis found that CHRNA7 expression is associated with JAK2-STAT3 signaling in different cancers, we test the hypothesis that nicotine enhances tumor-initiating capacity by activating CHRNA7 and subsequently the JAK2/STAT3 pathway." (PMID 33603170, 2021). "Restoration of STING activity by for example blocking JAK2/STAT3 pathways may increase the efficacy of cancer immunotherapies in particular therapies using STING agonists." (PMID 33790360, 2021). "However, AG490 can effectively block the activation of the JAK2/STAT3 signaling pathway in different cancer cell lines 28,31." (PMID 33123268, 2020). "The activation of JAK2/STAT5 pathway has been reported in different types of cancers." (PMID 32086862, 2020).
cancer (continued). "Inhibition of STAT3/JAK2 pathway has been formerly proved to induce apoptosis in cancer cells." (PMID 33680016, 2020). "Finally, the anti-cancer efficacy of AT-I in CRC is essentially mediated by inactivation of the JAK2/STAT3 signaling pathway." (PMID 32273843, 2020). "Previous study showed that PAK1 can activate IL‐6 expression via JaK2 activation in cancer stem cell, whether JaK2 involved in the PAK1‐mediated IL‐6 production needs further study to confirm." (PMID 33124146, 2020). "Interestingly, a combination consisting of trastuzumab and ruxolitinib – a JAK1/JAK2 inhibitor – demonstrated a synergistic cancer inhibition in mouse xenografts of HER2 transformed BC cell lines." (PMID 33193699, 2020). "JAK2/STAT3 pathway is frequently upregulated in many human cancers." (PMID 33123268, 2020). "Consequently, it potentiates the inhibitory effect of IFN-α, a potent antiproliferative factor, on cancer cell viability by activating JAK2/STAT3 signaling pathway through inhibition of 26S proteasome-mediated IFNAR1 degradation." (PMID 31100782, 2019). "As cancer recurrence can occur due to the proliferation and colonization of viable cancer cells after RT, we evaluated whether JAK2 knockdown and STAT3 inhibition are capable of blocking the clonogenic potential of surviving cells after RT." (PMID 31511084, 2019). "Thus, we next investigated the correlation between CCND2 and JAK2 in cancer tissues and matched normal tissues from CRC patients to analyze the expression of both CCND2 and JAK2." (PMID 31511084, 2019). "Besides, the BRCA1 and JAK2 that co-cited with ‘cancer’ and ‘breast’ for many times were also missed by the DawnRank." (PMID 31888619, 2019). "Therefore, further investigating the mechanism of JAK2 with regard to CSC metastasis will be promising for the development of future cancer therapies." (PMID 31511084, 2019). "To validate whether these genes are actually involved in JAK2/STAT3-mediated cancer cell stemness, we evaluated mRNA expression patterns in well-differentiated monolayer-cultured or CSC-enriched sphere-propagated HCT116 cells with or without JAK2 silencing." (PMID 31511084, 2019). "Importantly, the levels of JAK2 autophosphorylation and activation are increased in many cancers, particularly those of a haematopoietic origin." (PMID 31817106, 2019). "(B) Heatmap analysis of correlation of PDGFRβ with JAK2 levels in pan-TCGA cancer samples." (PMID 30777101, 2019). "For these reasons, our results carefully suggest that the anti-cancer effect of quercetin may be partly related to the inhibition of JAK2 and PKCδ." (PMID 31652815, 2019). "Therefore, our discovery of the JAK2/STAT3/CCND2 axis in CSCs will have broad applications in multiple types of cancers." (PMID 31511084, 2019). "Dysregulation of JAK2/STAT3 signaling pathway has been described in many cancers including NSCLC." (PMID 31754348, 2019). "Finally, we demonstrate that the clinically available JAK2 inhibitor Ruxolitinib synergises with cisplatin in inducing apoptosis, highlighting JAK2 as a promising therapeutic target in HPV-driven cancers." (PMID 31817106, 2019). "JAK2/STAT3 seem to be the most popular targets in cancer treatment." (PMID 30109213, 2018). "JAK2/STAT3 signaling pathway shows a pivotal role in cancer cell survival and disease progression." (PMID 30356255, 2018). "After activation, JAK2 kinase can phosphorylate STAT3, which then translocates to the nucleus to enhance the levels of downstream genes, including anti-apoptotic genes that are implicated in human cancer development." (PMID 28570563, 2017). "The present study aims to investigate the roles that TGF-β and IL-6/JAK2/STAT3 signaling play in cancer cell-MF interaction and how this interaction could influence cancer cell proliferation and disease progression in both in vitro and in vivo systems." (PMID 28819126, 2017).